HOOK1 (hook microtubule tethering protein 1)
Description:
Component of the FTS/Hook/FHIP complex (FHF complex). The FHF complex may function to promote vesicle trafficking and/or fusion via the homotypic vesicular protein sorting complex (the HOPS complex). FHF complex promotes the distribution of AP-4 complex to the perinuclear area of the cell. Required for spermatid differentiation. Probably involved in the positioning of the microtubules of the manchette and the flagellum in relation to the membrane skeleton (By similarity).
Synonyms: HK1
Tractability: PROTAC: ubiquitination databases record sites on it; its protein half-life has been measured.
Gene: Protein-coding gene on chromosome 1 (59,814,786 to 59,876,369, forward strand). Ensembl gene ENSG00000134709.
Subcellular location: Cytoplasm; Cytoplasm, cytoskeleton
Gene Ontology:
Molecular function: identical protein binding; protein binding; protein homodimerization activity; dynein light intermediate chain binding; microtubule binding; actin binding
Biological process: early endosome to late endosome transport; endosome organization; endosome to lysosome transport; lysosome organization; protein localization to perinuclear region of cytoplasm; cytoplasmic microtubule organization; cytoskeleton-dependent intracellular transport; protein transport along microtubule
Cellular component: cytoplasm; FHF complex; HOPS complex; centrosome; cytoskeleton; microtubule cytoskeleton
Genetic constraint (gnomAD): Loss-of-function variants: 21 observed, 31.16 expected, observed/expected ratio (o/e) 0.67, 90% interval 0.48 to 0.97. The upper end of that interval is the gene's LOEUF score, 0.97, which puts it in group 4 of 6, group 1 being the genes least tolerant of losing a copy. Missense variants: 353 observed, 364.07 expected, observed/expected ratio (o/e) 0.97, 90% interval 0.89 to 1.06. Synonymous variants: 143 observed, 121.67 expected, observed/expected ratio (o/e) 1.18, 90% interval 1.02 to 1.35.
Homologues: Orthologues: chimpanzee HOOK1 (99% identical), macaque HOOK1 (99% identical), rabbit HOOK1 (96% identical), dog HOOK1 (96% identical), mouse Hook1 (93% identical), guinea pig HOOK1 (92% identical), rat Hook1 (91% identical), tropical clawed frog hook1 (69% identical), zebrafish hook1 (64% identical), Drosophila melanogaster Girdin (18% identical), Caenorhabditis elegans grdn-1 (17% identical). Paralogues in human: HOOK3 (58% identical), HOOK2 (47% identical), CCDC88A (29% identical), CCDC88C (28% identical), CCDC88B (21% identical).